ERBB2 (erb-b2 receptor tyrosine kinase 2)
Diseases named in the same sentence as ERBB2 in open-access papers (continued):
Sharing a sentence is not in itself a finding about the gene and the disease.
breast cancer (continued). "We have demonstrated that HRGβ1 can partially overcome the inhibitory effects of gefitinib monotherapy on growth and invasion of tamoxifen-resistant MCF-7 breast cancer cells through promotion of erbB3/erbB2 heterodimerization and activation of the PI3K/AKT signalling pathway." (PMID 17686159, 2007). "Integrin α6β4 co-localises and associates with ErbB2 in breast cancer cells (but probably not in normal cells), resulting in a gain of function that enhances proliferation and migration." (PMID 17251051, 2007). "In addition, LN-5 is known to favor breast carcinoma progression and the expression of growth factor receptors such as ErbB2 can be regulated at the translational level." (PMID 17637831, 2007). "Mutations in the ataxia-telangiectasia mutated (ATM) and checkpoint kinase 2 (CHEK2) genes and amplification of the v-erb-b2 avian erythroblastic leukemia viral oncogene homolog 2 (ERBB2) gene have been suggested to have an important role in breast cancer aetiology." (PMID 17132159, 2006). "Breast cancer subtype classification is closely related to ER status, with a high proportion of luminal A/B and normal-like tumors having ER-positive protein overexpression, whereas basal-like and ERBB2 tumors have a higher proportion of ER negativity." (PMID 16846532, 2006). "One group found a relationship between poor breast cancer prognosis and common haplotypes in the ERBB2 gene, but to our knowledge, nothing has been reported regarding the association between common haplotypes in the ATM and CHEK2 genes and breast cancer survival or tumour characteristics." (PMID 17132159, 2006). "Second, MMP-2 levels are increased by overexpression of erbB2; previous studies have shown that erbB2 and Muc1 expression are mutually exclusive in mammary tumors, implying that MMP2 might be part of a transcriptional profile linked to low MUC1 levels." (PMID 16846534, 2006). "Our results indicate that common variants in the ATM, CHEK2 or ERBB2 genes are not involved in modifying breast cancer survival or the risk of tumour-characteristic-defined breast cancer." (PMID 17132159, 2006). "Common haplotypes in the ERBB2 gene thus do not seem to affect the risk of breast cancer, although results regarding the I655V common variant in the ERBB2 gene have been conflicting." (PMID 17132159, 2006). "At least a third of all ErbB2-positive breast cancers are also ER-positive, and because this breast cancer subgroup appears more refractory to all forms of endocrine therapy, it has attracted considerable attention among basic and clinical breast cancer investigators." (PMID 16784538, 2006). "Using the intrinsic set of approximately 500 genes derived in the Norway/Stanford breast cancer data, we validated the existence of five molecular subtypes – basal-like, ERBB2, luminal A/B and normal-like – and characterized these subtypes extensively with the use of conventional clinical variables." (PMID 16846532, 2006). "Modern breast cancer treatments are based on these two validated biomarkers since ErbB2-positive breast cancers are treated with the ErbB2-targeted antibody, trastuzumab (Herceptin©), while ER-positive breast cancers are treated with either antiestrogens or estrogen-ablating aromatase inhibitors." (PMID 16784538, 2006). "Thus, stem/progenitor cells for luminal and ErbB2-positive breast cancers, which represent the majority of breast cancers, remain to be identified." (PMID 17062128, 2006). "For example, ErbB2 amplicon on 17q21 is amplified in 20–30% of breast cancers." (PMID 17147824, 2006). "We have previously shown that common alleles in ERBB2 are not involved in breast cancer susceptibility." (PMID 17117180, 2006). "ERBB2 overexpression in women with both node-positive and node-negative breast cancer is associated with a poor prognosis, and several studies have found a correlation between ERBB2 overexpression and a shorter disease-free period and shorter overall survival." (PMID 15743507, 2005).
breast cancer (continued). "While others have reported that transgenic mice bearing activated forms of rat c-neu/erbB2 have co-expression of erbB2 and endogenous erbB3 in mammary tumors, direct physical and functional interactions between these two species receptors have not previously been reported." (PMID 16168116, 2005). "In summary, we conducted a large case–control study of ERBB2 and breast cancer." (PMID 15743501, 2005). "Epithelial phenotype is associated with breast cancers that express neither ER nor erbB2, a feature that also occurs in BRCA1-mutation carriers." (PMID 15642173, 2005). "The EGF/ERBB2 signaling pathway is clinically relevant in breast cancer." (PMID 16457699, 2005). "Akt is frequently upregulated in ErbB2 amplified or overexpressing human breast cancer cells." (PMID 16168116, 2005). "We used FISH on a series of 175 formalin-fixed paraffin-embedded breast carcinomas to detect ERBB2 amplification, using a dual-probe system for the simultaneous enumeration of the ERBB2 gene and the centromeric region of chromosome 17, as well as using IHC to detect overexpression." (PMID 15743507, 2005). "Furthermore, the overexpression of ErbB-2/HER-2, an important predictive factor in breast cancer, is also closely associated with increased angiogenesis." (PMID 14710236, 2004). "The modulation of IFN signalling in ErbB-2-overexpressing breast cancers warrants further investigation, and may possibly identify new therapy targets, and/or allow optimisation of current therapies that utilise IFNs to treat patients with cancer." (PMID 14710226, 2004). "Preclinical work has demonstrated that IGF-1R could be used as a successful co-target with EGFR and HER2/erbB2, and in the latter study, synergistic inhibition of proliferation was observed in co-targeted breast cancer cells." (PMID 15150607, 2004). "The present data support the hypothesis that ERBB2 amplification and/or overexpression enhance signalling pathways that may lead to increased production of gelatinases in c-erbB-2-positive breast cancers with higher metastatic potentialities." (PMID 15054465, 2004). "Our results suggest that the IGF-IR receptor may mediate patient response to breast cancer therapies targeting ErbB2." (PMID 15305194, 2004). "AP-2 levels are high in most breast cancer cells overexpressing ERBB2." (PMID 12942124, 2003). "Chimeric constructs containing a single-chain antibody directed against the human ErbB-2 receptor have been previously demonstrated to redirect T-cell specificity towards mouse epithelial cells transformed to express the human ErbB-2 and human ErbB-2+ MDA-MB453 breast cancer cells." (PMID 12698199, 2003). "Together, these data clearly indicate that Srsf3 functions differently in the tissue context by altering the expression of specific sets of genes which could partially explain the different roles Srsf3 might play in the Erbb2 breast cancer from DEN-induced liver cancer." (PMID 40568073, 2025). "More research is needed to identify the strategies and practices that contributed to the narrowing of disparities in the receipt of ERBB2-targeted therapy, as such strategies may be implemented to improve the quality and equity of breast cancer care more broadly." (PMID 40310643, 2025). "To investigate whether the expression of ERBB2 i14e contributes to trastuzumab resistance in other types of cancers, not limited to GBC, we assessed ERBB2 i14e levels in a secondary trastuzumab-resistant breast cancer cell line SKBR344 and found identical results with increased ERBB2 i14e." (PMID 39948369, 2025). "Therefore, the aim of this study was to explore, through a combination of bioinformatic intracellular pathway analysis (BIPA) and molecular docking simulations, the binding affinity of various nsBBs for three receptors associated with breast cancer: ADRB2, ERBB2, and NPYR." (PMID 41150737, 2025).
breast cancer (continued). "Similarly, in colorectal cancer, YBX1 binds to the promoter and acts as a transcriptional activator of the EGFR gene, mediating resistance to anti-ERBB2 therapy and preventing apoptosis in ERBB2-overexpressing breast cancer cells through a complex RSK-dependent mechanism." (PMID 40799245, 2025). "Notably, TPD52 is a survival factor for breast cancer cells that ERBB2 has increased." (PMID 39757112, 2025). "Breast cancer can be classified into four subtypes based on the expression of estrogen receptors (ERs), progesterone receptors, and ErbB2 (HER2) receptors: luminal A (ER+ and HER2-), luminal B (ER+ and HER2+), ErbB2/HER2-positive (ER- and HER2+), and triple-negative (ER- and HER2-)." (PMID 41161384, 2025). "For drug response assessments, the threshold at which c-Myc switches from supporting cell survival to inducing irreversible cell cycle arrest in relation to ErbB2 levels could inform the development of more effective molecular-targeted treatment strategies for breast cancer." (PMID 41161384, 2025). "This systematic review and meta-analysis compares the incidence of cardiotoxic effects of antibody-drug conjugates vs standard chemotherapy regimens for erb-b2 receptor tyrosine kinase 2 (ERBB2)–positive locally advanced or metastatic breast cancer (BC)." (PMID 41206886, 2025). "Additionally, in HER2-positive breast cancer cells, tumor cells may escape ERBB2 inhibition through bypass signaling pathways such as PI3K/AKT and MAPK, enhancing the growth and proliferation of tumor cells." (PMID 39911393, 2025). "HER2 overexpression is driven by amplification of the ERBB2 gene located at the long arm of human chromosome 17 (17q12) The humanised monoclonal antibody trastuzumab is a component of standard of care for multiple different treatment regimens in HER2-positive breast cancer." (PMID 40165206, 2025). "Interestingly, stratification of this analysis by breast cancer receptor subtype demonstrated that the observed association was limited to the most traditionally indolent subtype (hormone receptor–positive and ERBB2-negative; OR, 1.12; 95% CI 1.04–1.21)." (PMID 41035100, 2025). "Further studies indicated that ERBB2 i14e could also endow cancer cells with irresponsiveness to trastuzumab, one of the most important targeted drugs for ERBB2 used in clinical treatment for breast cancer for over 20 years." (PMID 39948369, 2025). "Approximately 10% of breast cancers (BC) express the estrogen receptor (ER) and overexpress the human growth factor receptor 2 (HER2, also known as ERBB2)." (PMID 41423595, 2025). "Breast cancer is classified into different molecular subtypes based on the expression characteristics of estrogen and progesterone receptors (ER and PR) and human epidermal growth factor receptor 2 (HER2; ERBB2): Luminal A, Luminal B, HER2(+), and triple-negative breast cancer (TNBC)." (PMID 40724542, 2025). "The experimental outcomes also may potentially be affected by compensatory upregulation of other PFKFB isoforms such as PFKFB4 which likely explains the differences that we observed in the growth of the more gradual K-ras-driven lung tumor model relative to the Erbb2 mammary tumor model." (PMID 39001392, 2024). "Based on the status of ER, PR, Ki-67 and HER2 (ERBB2), BC characterized by significant heterogeneity can be categorized into four major subtypes, namely, luminal A, luminal B, HER2-positive and triple-negative breast cancer (TNBC)." (PMID 38397395, 2024). "Also a TRAPPC9 dependent, NF-κB signalling pathway mediated Lapatinib resistance could be revealed in Lapatinib-resistant ERBB2-amplified breast cancer cell lines." (PMID 39654143, 2024). "In addition, evidence in hormone receptor positive (HR+) breast cancers suggest potential roles for upstream receptor overexpression (FGFR2) and de novo mutations in RAS, AKT1, AURKA, CCNE2, and/or ERBB2 in the activation of ERK following acquired CDK4i/6i resistance." (PMID 38066089, 2024).
breast cancer (continued). "Current clinical practice categorizes breast cancer into three subtypes based on immunohistochemistry (IHC) tests for estrogen receptor (ER), progesterone receptor (PR), and erythroblastic oncogene B/human epidermal growth factor receptor 2 (ErbB2/HER2) expression." (PMID 38892243, 2024). "Additionally, HER2 in the nucleus can interact with STAT3, thereby regulating the transcription of STAT1 and CCND1 and acting as a coactivator of microRNA 21 (miR-21) in breast cancer, revealing a novel function of nuclear ErbB-2 as a regulator of microRNAs expression." (PMID 39404930, 2024). "Breast cancers are highly heterogeneous at both the cellular and molecular levels and are classified clinically by immunohistochemistry and/or in situ hybridization-based detection of estrogen receptor-α (ER-α), progesterone receptor (PR), and HER2/ErbB-2 expression." (PMID 39335212, 2024). "Notably, ERBB2, also known as HER2, has been well-documented for its overexpression in breast cancer and is a validated therapeutic target, as is EGFR, which is implicated in various cancers including breast cancer." (PMID 38306344, 2024). "Human epidermal growth factor receptor 2-positive (HER2+) breast cancer (BC), constituting around 20% of all BC, is characterized by the amplification of the ERBB2 gene on chromosome 17q12, resulting in an overexpression of the HER2 protein." (PMID 39273217, 2024). "Breast cancer exhibits high heterogeneity and is clinically categorized into five intrinsic subtypes based on the expression of the estrogen receptor (ER), the progesterone receptor (PR), epidermal growth factor 2 (ERBB2), and the Ki67 proliferation marker protein (MKI67)." (PMID 39065193, 2024). "Breast cancer (BC) is a common heterogeneous solid tumour, that can be divided into four major subtypes: luminal A and luminal B subtypes, ERBB2 subtypes, basal‐like subtypes." (PMID 38299307, 2024). "In addition, it would also be interesting to investigate the other promoters, especially those described to be mostly breast cancer tissue-specific, such as ErbB2 and MUC1, or a BCSC-specific promoter, like MDR, to further enhance the therapeutic potential of OAd expressing hNIS." (PMID 38675909, 2024). "Notably, patients with ERBB2-amplified or overexpressing breast cancer can derive therapeutic benefits from ERBB2-targeted interventions, encompassing anti-ERBB2 antibodies (e.g., trastuzumab and epratuzumab) and small-molecule tyrosine kinase inhibitors (e.g., lapatinib and neratinib)." (PMID 38245506, 2024). "In addition, ERBB2 somatic mutations have been identified in ERBB gene-amplification-negative human breast cancers; many of these are activating mutations, and thus, ERBB2 somatic mutation is an alternative mechanism to activate HER2 in breast cancer." (PMID 38787171, 2024). "Constituting 15%-20% of all breast cancers (BCs), triple-negative breast cancer (TNBC) is characterized by the absence of estrogen and progesterone receptors and the non-amplification of the ERBB2 gene, which encodes human epidermal growth factor receptor 2 (HER2)." (PMID 38910707, 2024). "ERBB2 activating mutations, on the other hand, are often detected in breast carcinomas lacking ERBB2 amplification and may be found also in other histological subtypes, such as lobular carcinoma." (PMID 38015260, 2024). "For contemporary breast cancer actionability, PIK3CA mutation is a biomarker for the FDA-approved PI3Kα inhibitor alpelisib, AKT1 mutation is indicated for agents such as capivasertib (AZD5363) and ipatasertib, and ERBB2 mutation for tyrosine kinase inhibitor neratinib." (PMID 37760445, 2023).
breast cancer (continued). "We noticed ERBB2 (HER2) among the plasma membrane proteins with increased expression in G0 and decided to further study this protein because of its known importance in other malignancies, especially breast cancer and because of the many drugs available that target it." (PMID 36805918, 2023). "Therefore, HER2-positive breast cancer showing an increased vascular index on Microvascular US may be associated with rs1136201 in ERBB2 and may be expected to have a more favorable response to targeted therapy." (PMID 37120792, 2023). "Also, more than three-fourths of ERBB2-mutant breast cancers were clinically HER2-negative." (PMID 37760445, 2023). "NF1 loss-of-function mutations, RTKs mutations such as ERBB2 activating mutations, as well as alterations in other MAPK pathway genes (EGFR, KRAS, BRAF, and MAP2K1) were found to be enriched in endocrine-resistant advanced ER+ breast cancer compared to early-stage ER+ breast cancer." (PMID 38003387, 2023). "Taken all together, therapeutic oligonucleotides are a potential alternative to antibodies and small molecule inhibitors to silence the expression of the ERBB2 gene and could overcome some of the inconvenients of the standard treatments for HER-2 positive breast cancers." (PMID 37108234, 2023). "Hence, we hypothesized that Shc3 might act as a novel adaptor between EphA2 and ErbB2 in breast cancer cells." (PMID 36880347, 2023). "Hence, it was proposed that individuals with ErbB2-positive breast cancer might benefit from pharmacological inhibition of PTPN1 activity in combination with anti-ErbB2 therapies." (PMID 37936713, 2023). "With the knowledge that the treatment landscape for breast cancer is changing rapidly, it will be of important clinical significance to use such integrative analyses to distinguish between resistant tumors primarily driven by ERBB2 aberrations and those driven by downstream pathways." (PMID 37968696, 2023). "ERBB2 overexpression and ERBB2 amplification were defined according to the recommendations of the American Society of Clinical Oncology/College of American Pathologists (ASCO/CAP) for breast cancer and gastric carcinoma (GC), revealing scores of 2+ and 3+ in 10.2% and 41.8% of UTUCs, respectively." (PMID 37173881, 2023). "Thus, ErbB2 downregulates BLNK in detached breast cancer cells." (PMID 35933456, 2022). "Moreover, NOTCH4 downregulation is linked to suppressed proliferation and induced apoptosis of Erbb2-negative breast cancer cell lines." (PMID 35136410, 2022). "Researchers had proved that miR-1296-5p could function as an inhibitor in gastric cancer by targeting cyclin-dependent kinase 6 and epidermal growth factor receptor, ERBB2-positive breast cancer by downregulating ERBB2, in osteosarcoma through repressing notch receptor 2 expression." (PMID 35287543, 2022). "Alterations in the ErbB family (namely ErbB1 (EGFR/HER1), the orphan receptor ErbB2 (HER2 or Neu), ErbB3 (HER3), and ErbB4 (HER4)) have been associated with BC incidence and poor prognosis and mutations of ErbB effectors are among the most common genetic abnormalities associated with breast cancer." (PMID 36233192, 2022). "Hence, BLNK upregulation blocks tumorigenicity of ErbB2-positive breast cancer cells in vivo." (PMID 35933456, 2022). "In addition, by cooperating with ErbB2, a loss of Par3 can inhibit the junction stability of E-cadherin and disrupt cell–cell junctions and cell–cell cohesion through the Tiam1/Rac-GTP pathway, resulting in accelerated metastasis of breast cancer in vivo." (PMID 35875120, 2022). "Although the roles of upregulation of CHK in the development of breast tumors is unknown, the mechanism that trastuzumab induces CHK mediated ErbB2 degradation, leading to the inhibition of breast cancer cell growth may be used as a novel strategy to treat ErbB2-positive breast cancers." (PMID 36568988, 2022).